IL15 (interleukin 15)
Diseases named in the same sentence as IL15 in open-access papers (continued):
Sharing a sentence is not in itself a finding about the gene and the disease.
tumor (continued). "IL-12, IL-15, and immune checkpoint inhibitors have individually shown great potential as anti-cancer therapeutics, and antibody-based checkpoint inhibitors are readily available and display enhanced anti-tumor activity when co-administered with T-VEC or with oncolytic Newcastle disease virus." (PMID 33182232, 2020). "Moreover, since expression of IL‐12, IL‐15 and IL‐18 is upregulated, this may lead to formation of NK memory cells in the tumor microenvironment which needs to be further explored." (PMID 32821382, 2020). "Increases in PD-L1 expression can occur on SCC cells as a result of mutations in tumor cell signaling pathways or exposure of tumor cells to inflammatory cytokines IL-1, IL-6, GM-CSF, IFNγ, TNFα, and VEGF and the gamma-chain cytokines IL-2, IL-7, IL-10, IL-15, and IL-21." (PMID 31554151, 2019). "Blocking IL-2 and IL-15 activities in the context of IL-1β administration completely abrogated the ability of Pmel-1 cells to control tumor growth and shortened the life span of tumor-bearing mice, suggesting a strong dependence of IL-1β enhancement of T cell antitumor function on IL-2 and IL-15." (PMID 31405895, 2019). "Also, in this model, IL-15-deficient animals (which lack ILC1 cells because IL-15 is important for their generation) showed accelerated tumor growth when compared to mice lacking CD8+ T cells." (PMID 31366131, 2019). "Both IL-15 and IL-12/15/18 activated NK cell anti-tumor effects in vivo were transient when these cells were used alone, supporting the importance of optimizing NK cell infiltration and/or persistence at the tumor site to reach high number of effector cells able to rapidly kill tumor cells." (PMID 31699153, 2019). "Upon administration, we suspect that these IL-21/IL-2-expanded TILs or TRUCKs would be best maintained by engineering them to secrete IL-7 and IL-15, which we hypothesize will further promote their persistence and memory recall responses to prevent tumor relapse in patients." (PMID 30842774, 2019). "In addition, CAR-NK cells, genetically modified to over-express either molecules mediating tumor killing or cytokines able to sustain NK cell proliferation/function (e.g., IL-15), may represent a further valuable tool for adoptive cell therapy of cancer." (PMID 32010130, 2019). "Additionally, once Deep IL-15 primed CTLs are exposed to antigen, they show prolonged antigen-specific activation, survival, and expansion, as well as persistent antigen- specific cytotoxicity, indicating the Deep IL-15 improves the durability of anti-tumor activity." (PMID 30400835, 2018). "Importantly, TH-/IL-15-based DNA vaccination resulted in an enhanced tumor remission in 45.5% of mice compared to controls (TH (16.7%), IL-15 (0%)) and reduced spontaneous metastasis (30.0%) compared to controls (TH (63.6%), IL-15 (70.0%))." (PMID 30452438, 2018). "Thus, it may be possible to improve anti- tumor efficacy through the generation of a molecule that targets IL-15 activity to the TME and potentially reduces immunosuppression and immune-related adverse events." (PMID 30400822, 2018). "Furthermore, the functionality of ascites-derived NK cells in terms of CD107a/IFN-γ activity was comparable to that of healthy donor peripheral blood NK cells, and stimulation with monomeric IL-15 or IL-15 superagonist ALT-803 potently improved their reactivity towards tumor cells." (PMID 30410679, 2018). "In fact, although IL-15 displays antitumour activities against solid cancers in experimental animal models and has been recognized as one of the most encouraging immunotherapeutic drugs, only a small number of studies have demonstrated the effectiveness of IL-15 against haematologic tumours." (PMID 29089667, 2017). "Therefore, CD215+ myeloid cells respond to IL-15 and promote tumor growth." (PMID 29255466, 2017). "Additionally, the over expression of PTEN suggest that IL-15 could increase the expression of tumor suppression genes." (PMID 28379958, 2017).
tumor (continued). "Based on the increased expression of cytokines specific for activated DC (IL-12, IL-15 and IL-18) we have shown partial stimulation of specific cell types involved in cell-mediated immunity, although the only significant effect of immunization on the tumor size has been confirmed in IL-12." (PMID 28381295, 2017). "Next, we discuss IL-4 and IL-15 involvement in the generation of innate CD8(+) T cells and particularly its possible dependency on the promyelocytic leukemia zinc-finger factor expressing iNKT cells, an innate T cell subset well documented for its susceptibility to tumor immune subversion." (PMID 28396661, 2017). "The increase of PTEN, a tumor suppressor, shows that IL-15 may induce an anti-tumor phenotype." (PMID 28379958, 2017). "Thus, expanding Vγ2Vδ2 T cells with pulse zoledronate stimulation and either IL-18/IL-2, IL-21/IL-15, or IL-21/IL-2 could increase their anti-tumor immunity." (PMID 28239463, 2017). "Therefore, whether IL-15 promotes human CD215+ cell expansion and whether IL-15 facilitates tumor growth in clinical application require further investigation." (PMID 29255466, 2017). "However, our results shed light on the possibility that IGF-1 may be an important candidate that IL-15 facilitates tumor growth." (PMID 29255466, 2017). "Therefore, we conclude that IGF-1 may be an important candidate that IL-15 facilitates tumor growth." (PMID 29255466, 2017). "In addition, IL-15 administration reduced the number of infiltrating F4/80+/CD68+ cells in the tumor mass, in line with the hypothesis of a preferential NK-myeloid cell communication mediated by IL-15." (PMID 29286001, 2017). "However, there are other reports indicating that IL-15 protects tumor cells from apoptosis." (PMID 29255466, 2017). "We further tested whether IL-15 could directly promote the proliferation of tumor cells." (PMID 29255466, 2017). "Here, we investigated whether and how IL-15 contributes to myeloid cell-mediated tumor progression." (PMID 29255466, 2017). "Thus, arguing that free IL15 alone is not only sufficient in anti-tumor therapies, but could potentially be better tolerated as a therapeutic by predominantly targeting NK cells and avoiding overwhelming CD8+ T cell activity." (PMID 26822794, 2016). "Next to IL-2, other γc-cytokines, such as IL-7, IL-15, and IL-21, have been described to play a role in memory T cell formation, proliferation, and survival, yet result in a lower degree of T cell differentiation but are still able to enhance anti-tumor responses." (PMID 27656185, 2016). "In the current study, we demonstrated for the first time that the combination therapy of the IL-15 superagonist ALT-803 with a monoclonal antibody B10G5 targeting soluble MIC confers a significant survival benefit in comparison to monotherapy in sMIC+ tumor hosts." (PMID 26625316, 2016). "Furthermore, IL15 plays an important role in various diseases, including tumor modulation." (PMID 27438147, 2016). "Expressing IL15 under the control of the CD11c promoter ensures its expression in cell types, which physiologically do express the cytokine in a tightly regulated manner and also ensures the expression of the cytokine at organs and sites in which tumor immunity is occurring." (PMID 26822794, 2016). "Whether and how IL-15 DCs harness the anti-tumor potential of NK cells remains to be examined." (PMID 25951230, 2015). "The ability of IL-15 DCs to specifically harness the CD56bright NK cell compartment may be of particular relevance for immunotherapy since CD56bright NK cells have been identified as the predominant tumor-infiltrating NK cell population." (PMID 25951230, 2015). "Furthermore, to promote their clinical application, our DC can be loaded with different kinds of tumor antigens and since the expansion and survival effects of IL-15 on CTLs are antigen-independent, our DC vaccine can be used against a broad range of tumor types." (PMID 26675759, 2015).
tumor (continued). "The in vivo delivery of transgene IL-15 into DC, which co-express full-length transgenic tumor Ag to allow for simultaneous DC presentation of Ag to T cells, may result in safer and more effective therapeutic vaccines that constitute an urgent, but as yet unmet, clinical need." (PMID 25941586, 2014). "Interestingly, rapid tumor growth immediately followed the growth inhibitory effects of soluble IL-15 leaving open the possibility that administration of IL-15 may simultaneously promote tumor cell growth and cell mediated tumor immunity in vivo." (PMID 24416335, 2014). "Thus, proliferating in the context of significantly reduced numbers of NK and CD8 cells, the malignant population of CD16/32HI LGLs within IL-15−/− tumors expressed elevated IL-1α and IL-1α-regulated transcripts and recruited activated tumor-infiltrating neutrophils." (PMID 24416335, 2014). "Production of IL-15 from oHSV could be self-limiting in certain tumor models." (PMID 24312353, 2013). "Therefore, IL-15 application in tumor therapy should always be approached with caution and should be preceded by a careful examination of its effects in the appropriate tumor cells in vitro." (PMID 22363690, 2012). "Indeed, if mice that had been gene transferred on day 1 were euthanized on day 19 after tumor cell inoculation, the number of observable liver metastases was drastically reduced by all the plasmids encoding IL-15, but not by the pApo A-I expression plasmid." (PMID 23285013, 2012). "Similarly, targeting molecules on tumor-specific T cells that are involved in the regulation of T cell survival and effector functions (e.g., IL-7, IL-15, activating antibodies to CD137, blocking CTLA-4) might translate into improved clinical outcomes." (PMID 24212804, 2011). "Interestingly, IL-21 selectively enhances the effector functions of IL-15-activated murine NK cells, further underpinning the importance of functional interactions between the two cytokines, and mediates potent in vivo anti-tumour responses." (PMID 19712464, 2009). "Conversely, NKG2D expression levels significantly increased as a result of combined treatment with IL-15 and IL-21, suggesting that the NK cell populations obtained under these culture conditions may represent suitable effectors for cell-based anti-tumour therapeutic approaches." (PMID 19712464, 2009). "For solid tumors, modifying CAR-NK cells through gene editing to continuously secrete IL-15/IL-21 or express chemokine receptors such as CCR2 and CXCR4 significantly strengthens their tumor-specific trafficking and infiltration potential." (PMID 41498114, 2026). "Anti-MICB-CAR-NK cells activate the tumor-killing ability of NK cells by targeting MICB and preventing MICB shedding; IL-15 enhances the activity of Anti-MICB-CAR-NK cells." (PMID 41516373, 2026). "NK cells activated with IL-12/IL-15, and IL-12/IL-15/IL-18 co-cultured with MHC- tumor cells, and in each cytokine combination with MHC+ tumor cells caused proliferation inhibition and lysis of tumor cells." (PMID 41840113, 2026). "RNA-seq analyses of tumor tissues from PDX models (Utd, FAP CAR-T, and FAP/IL-15 CAR-T groups) were conducted to profile gene expression changes." (PMID 41455698, 2025). "To evaluate the status of TILs after combination (IL-15, NIR-PIT) therapy and anti-PD-1 therapy, we analyzed the CD8+ T cells and Treg distribution inside the tumor tissue 4 days after NIR-PIT using immunohistochemical analysis." (PMID 41410776, 2025). "Mechanistically, the improved efficacy can be attributed, in part, to IL-15 and CCL19 enhancing T-cell infiltration at the tumor site and fortifying resistance to exhaustion within the tumor microenvironment." (PMID 40177238, 2025). "For example, IL-15 provided a less differentiated phenotype, with higher CD27 and CD28 expression, improving in vivo persistence and anti-tumor immunity in tumor-bearing hosts." (PMID 41346587, 2025).
tumor (continued). "Studies demonstrate that IL-15 inhibits activation-induced CAR-T cell death, restores effector function, and significantly enhances anti-tumor efficacy in vivo." (PMID 41455698, 2025). "IL-15 promotes the expansion and persistence of CAR-T cells, leading to improved anti-tumour activity." (PMID 40624498, 2025). "Cytokines like IL-12 or IL-15 can be engineered into CAR-NK cells to enhance their persistence and anti-tumor effects." (PMID 40260240, 2025). "In this study, we engineered CAR-T cells directed against EGFRvIII to secret human IL-15 and CCL19 and assessed their anti-tumor efficacy against GBM in an orthotopic mouse model." (PMID 40177238, 2025). "Consistent with our hypotheses, ACTM-838, the STACT chassis carrying a plasmid that encodes IL-15/IL-15Rα and a constitutively active form of STING, exhibited a significantly decreased acute systemic proinflammatory cytokine response compared to VNP20009 in tumor-bearing mice upon IV dosing." (PMID 41048107, 2025). "Multiplex immunofluorescence of PDAC tissues showed reduced CAF-derived IL-15 and diminished NK cell presence in regions with high CGRP+ nerve density (e.g., tumor periphery or perineural invasion sites)." (PMID 40948749, 2025). "Among immunotherapeutic agents, recombinant interleukin-15 (IL-15) is particularly promising due to its potent stimulation of natural killer (NK) cells and CD8 + T cells, which are crucial for anti-tumor immunity." (PMID 40552079, 2025). "For example, hIL15-ABD, a fusion of IL-15 with the albumin-binding domain (ABD), has been used to treat PDAC, enhancing anti-tumor effects and extending the drug’s half-life." (PMID 39958351, 2025). "IL-15 co-expression in CAR-engineered immune cells has emerged as a strategy to enhance in vivo persistence, metabolic fitness, and anti-tumor function, particularly in NK and T cell platforms." (PMID 40564987, 2025). "The in vivo persistence of FAP/IL-15 CAR-T cells was evaluated on days 7, 14, and 28 post-treatment by detecting CD3 expression in spleen and tumor tissues using flow cytometry." (PMID 41455698, 2025). "While a previous study introduced IL-15 and CCL19 into CAR-T cells and evaluated the anti-tumor effects using a zebrafish xenotransplantation model, mouse xenograft models remain the gold standard for preclinical evaluation of CAR-T cell therapy." (PMID 40177238, 2025). "On the one hand, TGF-β can directly inhibit the growth of tumor cells, while IFN-γ, IL-2, IL-12 and IL-15 enhance the cytotoxicity of lymphocytes or bone marrow cells to suppress the proliferation of tumor cells." (PMID 41333471, 2025). "Our data revealed significantly suppressed tumor progression and improved overall survival in mice administered FAP/IL-15 CAR-T cells relative to all other experimental cohorts." (PMID 41455698, 2025). "For instance, co-expressing IL-15 or IL-21 in CAR-T cells has been explored to enhance persistence and mitigate exhaustion, thereby improving their anti-tumour efficacy." (PMID 40624498, 2025). "DCs matured in the presence of IL-15 are being investigated as promising components of next-generation DC-based immunotherapies; however, these approaches may require combinatorial strategies to achieve clinically relevant immunity, given the complexity of tumor immune evasion." (PMID 41196843, 2025). "The antitumor effect of the B16-LX/IL(15 + 7) vaccine was tumor-specific, as the EL4-LX/IL(15 + 7) vaccine (i.e., irradiated EL-4 tumor cells loaded with LX/IL(15 + 7)) did not inhibit antigenically unrelated B16-F10 tumor growth." (PMID 40957993, 2025). "Soluble factors in the tumor microenvironment, such as TGF-β, can suppress NK cell activation by blocking the mTOR signaling pathway triggered by IL-15, reducing NK cell proliferation and cytotoxicity." (PMID 40260240, 2025).
tumor (continued). "These IL-15-expressing CAR T cells showed improved persistence, greater tumor infiltration, and higher cytokine production, including IL-2, IFN-γ, and TNF-α, compared to conventional CAR T cells." (PMID 40895575, 2025). "In conclusion, IL15-based NIR-PIT showed cytotoxic effects in vitro, and suppressed tumor proliferation, improved survival, and elicited host immune response in vivo." (PMID 40886193, 2025). "In preclinical research, it has been shown that PLGA nanoparticles loaded with IL-15 significantly increase IFN-γ production and NK cell infiltration, which restricts tumor progression." (PMID 40917849, 2025). "Although the anti-inflammatory role of IL-15 is not fully elucidated in veterinary species, previous studies have suggested that IL-15 can indirectly reduce inflammatory cytokines through immune modulation, supporting its potential to alleviate tumor-associated inflammation." (PMID 40552079, 2025). "For example, IL‐15 transduction in CAR‐T cells enhances their expansion, persistence, and anti‐tumor activity, particularly in the immunosuppressive environment of solid tumors." (PMID 40178455, 2025). "This allows IL-15 to be released only when CAR-T cells are activated, demonstrating effective tumor clearance in low-antigen density models." (PMID 40072049, 2025). "Numerous studies have focused on augmenting CAR-T cells with IL-15, which has been shown to enhance CAR-T cells expansion and maintain a phenotype believed to potentiate their in vivo anti-tumor activity." (PMID 40177238, 2025). "Responses to cytokines promoting T cell function (IL-1-β, IL-2, IL-7, IL-15, IFN-α1, IFN-β, IFN-ω, IFN-γ) were downregulated in T cell aggregates relative to the tumor core, macrophage and DC islands but upregulated compared to other niches." (PMID 41510257, 2025). "IL-15 stimulation amplifies CAR expression and cytokine secretion, improving tumor control in xenografts, particularly with repeated dosing." (PMID 40896423, 2025). "Antigen pulsing was performed by culturing the mDCs in the presence of cytokines rh-IL-4, rh-GMC-SF, rh-IL-6, rh-IL1b, rh-IL12, rh-IL-15, and rh-TNF-α and incubating 106 cells with 18 μg of tumor lysate or cultured cell lysate for 18 h." (PMID 40733726, 2025). "For example, the IL-15 agonist NKTR-255 has been shown to prolong NK cell survival and enhance tumor-killing activity in preclinical models." (PMID 40170852, 2025). "This therapy achieved a CR rate of 90% which significantly surpassed those previously reported with tumor-targeted PIT and intratumoral IL-15 administration or CD25-targeted NIR-PIT and systemic IL-15 administration despite the reduced dose of IL-15." (PMID 41410776, 2025). "Collectively, these findings support the conclusion that adoptive transfer of FAP/IL-15 CAR-T cells effectively inhibits tumor growth by concurrently promoting apoptosis and restraining both angiogenic activity and tumor cell proliferation." (PMID 41455698, 2025). "Collectively, these data suggest that stimulation by FAP antigen substantially increases pro-inflammatory cytokine secretion by FAP/IL-15 CAR-T cells, thus facilitating localized inflammatory responses and efficient tumor targeting." (PMID 41455698, 2025). "The combined action of IL-15 and CAR-NK effectively eliminated CD70-positive tumor cells and increased the survival rate of mice harboring CD70-positive tumors." (PMID 40705122, 2025). "For example, incorporation of a membrane-bound IL-15 (mbIL-15) into CAR T-cell platforms has been shown to enhance the survival and function of T-cell therapies in a hostile tumor microenvironment." (PMID 40519930, 2025). "Our data indicated that FAP/IL-15 CAR-T cell treatment significantly suppressed tumor growth and prolonged survival in xenograft-bearing mice compared to FAP CAR-T cells, FAP CAR-T cells combined with exogenous IL-15, and other controls." (PMID 41455698, 2025).